PSMD1 (proteasome 26S subunit, non-ATPase 1)
Diseases named in the same sentence as PSMD1 in open-access papers (continued):
Sharing a sentence is not in itself a finding about the gene and the disease.
infection (222 papers, 2008 to 2026). The state of being infected such as from the introduction of a foreign agent such as serum, vaccine, antigenic substance or organism. "Psmd1 and Psmd13, 26S proteasome regulatory subunits, were identified to be significant primarily during secondary infection." (PMID 25341656, 2014). "Furthermore, the numbers of linkages from primary to secondary infection for both Psmd1 and Psmd13 increased significantly, suggesting that the proteasome is more active during secondary infection, and is therefore more important in the adaptive immune response of zebrafish." (PMID 25341656, 2014). "Therefore, the identification of Psmd1 and Psmd13 in our constructed intracellular PPI networks for secondary infection indicates that the proteasome system plays a pivotal role in the zebrafish immune response." (PMID 25341656, 2014). "Co-IP assays confirmed the interaction between GANC and endogenous and exogenous PSMD1/PSMD2 in the non-infected group and upon H7N9 infection." (PMID 40263249, 2025).
cancer (36 papers, 2008 to 2025). A tumor composed of atypical neoplastic, often pleomorphic cells that invade other tissues. "For instance, the depletion of PSMD1 leads to the ubiquitination of cellular proteins, causing cell cycle arrest and eventually triggering cell death in cancer cells." (PMID 40534847, 2025). "Using cBioPortal to analyze multiple TCGA cancers, we previously reported that altered PSMD1 expression was associated with mutations or deep deletions in several different solid tumors, whereas PSMD3 was primarily associated with gene amplifications." (PMID 36498916, 2022). "For the cancers demonstrating significant differences in OS, we next associated PSMD1 and PSMD3 mRNA expression with clinicopathological characteristics using UALCAN." (PMID 34572038, 2021). "PSMD1 is clinically associated with human cancers and cancer cell aggressiveness." (PMID 38580756, 2024). "Additionally, PSMD1 is classified as an innate immune gene, and its up-regulation is strongly associated with the progression of different types of cancers." (PMID 38933262, 2024). "In contrast, patients with GBM, which demonstrated reduced PSMD1 expression compared with normal controls, were associated with structural variants and deep deletions, possibly explaining the reduced expression observed in this particular type of cancer." (PMID 34572038, 2021). "Evaluating cancer tissue for expression of the proteasome subunit PSMD1 may help identify patients at risk for relapse." (PMID 24593279, 2014). "According to our research, PSMD1 plays a pivotal role as a target molecule for GOLM1 in facilitating a pro‐cancer function in PCa." (PMID 39470578, 2024). "Using cancer cell lines overexpressing PSMD1, we found that PSMD1 depletion inhibited the removal of ubiquitinated proteins and cancer cell survival." (PMID 38580756, 2024). "Given its overexpression in cancer and its distinct poor prognostic value, PSMD1 is predicted to have a specific function in cancer cells, unlike normal cells, apart from the common cell survival mechanism in normal and cancer cells." (PMID 38580756, 2024). "Although the absence of animal experiments limits the direct clinical significance of targeted anticancer treatments, our study provides valuable information regarding the potential role of PSMD1 in cancer." (PMID 38580756, 2024). "As several reports have demonstrated the effects of PSMD1 on cancer growth and prognosis, we assessed its role in human cancer cells." (PMID 38580756, 2024). "Both small interfering RNAs (siRNAs) targeting PSMD1 were confirmed to inhibit cancer cell survival by over 90% in Huh7 and and over 99% in SNU475, compared with control-siRNAs." (PMID 38580756, 2024). "We revealed that the function of PSMD1 as a proteasome subunit is critical for survival of cancer cells." (PMID 38580756, 2024). "In live/dead staining, after three days of transfection with PSMD1 siRNA (two days for Huh7 cells), the red signal indicating dead cells increased in cancer cell lines, whereas the green signal indicating live cells remained intact in normal cells." (PMID 38580756, 2024). "Cancers demonstrating higher PSMD1 mRNA expression compared with controls included BRCA, which is consistent with previous reports." (PMID 34572038, 2021). "At the mRNA level, PSMD1 was found to be significantly differentially expressed in 14/24 (58%) TCGA cancers compared with normal controls." (PMID 34572038, 2021). "In our analysis, however, some of the cancer types showed a similar phenotype, demonstrating decreased OS with decreased PSMD1 or PSMD3 expression." (PMID 34572038, 2021). "EIF2S2 is an anabolic factor, while PSMD1 is a catabolic factor, both of which are correlated to poor cancer prognosis." (PMID 33379356, 2020).
cancer (continued). "PSMD1 plays a crucial role in regulating cancer occurrence and progression." (PMID 41562084, 2025). "We observed that ubiquitination was significantly increased by depletion of PSMD1 in cancer cells." (PMID 38580756, 2024). "The selective cytotoxic effects of PSMD1 depletion on cancer cells were not limited to HCC cells." (PMID 38580756, 2024). "Additionally, we analyzed the expression of PSMD1 in various human cancer tissues using The Cancer Genome Atlas (TCGA) database." (PMID 38580756, 2024). "In this study, we explored the role of PSMD1 in cancer cell ubiquitination and survival." (PMID 38580756, 2024). "Recent studies have identified PSMD1 as a potential prognostic marker in several cancers." (PMID 38104103, 2023). "Based on our recent data in CML and other types of cancers, we hypothesized that PSMD1 and PSMD3 mRNA expression would be upregulated in AML versus normal mononuclear cells (MNCs), and that high expression would correlate with a worse OS." (PMID 36498916, 2022). "The post-translational modifications of PSMD1 or PSMD3 could provide a starting point for targeting these proteins in cancer therapy." (PMID 34572038, 2021). "Altogether, mutations, amplification, or deep deletions in the genes encoding PSMD1 and PSMD3 could explain their differential expression in different types of cancers." (PMID 34572038, 2021). "Thus, there appears to be tissue-specific differences on the phenotype resulting from altered expression of PSMD1 or PSMD3 in different cancer types." (PMID 34572038, 2021). "We next sought to determine whether expression of PSMD1 or PSMD3 correlates with OS in various cancers." (PMID 34572038, 2021). "Alternatively, during oncogenesis as cancer cells rapidly divide, the increase in gene expression could be due to gene amplifications, where more copies of PSMD1 and PSMD3 are erroneously introduced during replication." (PMID 34572038, 2021). "Therefore, it is conceivable that PSMD1 plays an important role in regulating carcinogenesis and cancer progression." (PMID 31413756, 2019). "PSMD1 expression seemed to also affect the locoregional cancer control probability of our patients undergoing primary definitive radiotherapy and we propose that treatment outcome was predominantly driven by an impaired treatment efficacy based on an increased number of therapy resistant CSCs." (PMID 24593279, 2014). "Similarly to other 26S proteasome subunits, PSMD1 is overexpressed in human cancer cells." (PMID 38580756, 2024). "PSMD1 may play a crucial role in maintaining cellular homeostasis by supporting essential ubiquitination processes in cancers with high metabolic activity, thereby contributing to cancer cell survival." (PMID 38580756, 2024). "We investigated whether PSMD1 plays a critical role in cancer owing to its prognostic significance." (PMID 38580756, 2024). "However, PSMD1 has been reported to be overexpressed in other cancers." (PMID 31874600, 2019). "To investigate the functional role of PSMD1, we selected HCC cell lines overexpressing PSMD1 and examined the survival of cancer cells under PSMD1 depletion." (PMID 38580756, 2024). "We also previously showed that PSMD1 and PSMD3 mRNA expression are upregulated in other types of cancers compared with normal tissue, and that this often correlates with a worse prognosis." (PMID 36498916, 2022). "In the present study, we used publically available databases to assess the effects of altered PSMD1 and PSMD3 mRNA and protein expression on disease progression and OS for multiple different cancers." (PMID 34572038, 2021). "Our analysis revealed that differential expression of PSMD1 and PSMD3 is correlated with worse OS in several different cancer types." (PMID 34572038, 2021).
cancer (continued). "Altogether, these data confirm that PSMD1 and PSMD3 mRNA and protein are differentially expressed in multiple types of human cancers, similar to our recent findings in CML disease progression and TKI resistance." (PMID 34572038, 2021). "Future studies will determine the mechanism by which PSMD1 or PSMD3 are upregulated in CML and other types of cancers, and will interrogate their potential as novel therapeutic targets." (PMID 34572038, 2021). "Ultimately, we highlight PSMD1 and PSMD3 as potential therapeutic targets for the development of novel proteasome inhibitors to treat cancer patients with less toxicity." (PMID 34572038, 2021). "We propose that PSMD1 and PSMD3, both subunits of the 19S regulatory complex of the 26S proteasome, are proteins worthy of further investigation for cancer prognosis and therapy." (PMID 34572038, 2021). "Our data implicate PSMD1 and PSMD3 as potential targets for combination therapies in myeloid malignancies and possibly other cancers." (PMID 33712704, 2021). "Altogether, these data indicate that high expression levels of PSMD1 and PSMD3 mRNA correlate with worse outcomes in multiple different cancers, with the exception of patients with DLBCL, STAD, and THYM." (PMID 34572038, 2021). "In our exploration of prognostic factors in HCC, the 26s proteasome subunit, non-ATPase 1 (PSMD1) protein emerged as a significant contributor, demonstrating its potential as a therapeutic target in this aggressive cancer." (PMID 38580756, 2024). "Similarly, we found that PSMD1 and PSMD3 mRNA expression is upregulated in multiple cancer types compared with normal tissue." (PMID 36498916, 2022). "In the present study, we comprehensively analyzed the expression and prognostic value of PSMD1 and PSMD3 across multiple cancer types using data from The Cancer Genome Atlas (TCGA) and the Clinical Proteomic Tumor Analysis Consortium (CPTAC), comparing expression with OS." (PMID 34572038, 2021). "The observation that PSMD1 and PSMD3 are upregulated in multiple different cancer types suggested that they may also play a role in outcomes." (PMID 34572038, 2021). "Altogether, our data suggest a role for PSMD1, PSMD3, and STAT3 in regulating NF-κB expression and activity in CML and TKI resistance, and implicate them as potential targets for the treatment of hematologic malignancies and possibly other forms of cancer." (PMID 33712704, 2021). "PSMD1, PSMD3, and the signaling pathways regulated by them, could be novel molecular targets for improved cancer therapy." (PMID 34572038, 2021). "Altogether, our data suggest that PSMD1 and PSMD3 may be novel putative targets for cancer prognosis and therapy that are worthy of future investigation." (PMID 34572038, 2021). "Although PSMD1 is a well-known component of the 19S regulatory particle, and its overexpression has been reported in some cancers, its intrinsic function or specific role in cancer has not been well studied." (PMID 38580756, 2024). "To investigate the involvement of PSMD1 in the pathogenesis of HCC, we analyzed its expression in tumor tissue specimens obtained from patients who underwent surgical resection at the Korea Cancer Center Hospital, using real-time PCR on liver tissue samples (n = 84)." (PMID 38580756, 2024). "Therefore, we hypothesized that PSMD1 and PSMD3 are potential targets for anti-cancer therapeutics and that their relevance stretches beyond CML to other types of cancers." (PMID 34572038, 2021). "Altogether, these findings suggest that PSMD1 and PSMD3 mRNA expression could serve as novel prognostic biomarkers for cancers affecting multiple different tissue types, especially for patients with KICH who are progressing from stage 3 to stage 4 of the disease." (PMID 34572038, 2021).
cancer (continued). "Additionally, PSMD1 and PSMD3 may be novel prognostic biomarkers for cancers affecting multiple different tissue types." (PMID 34572038, 2021). "In the case of patients in which the tumors could be resected successfully, expression of the proteasome subunit PSMD1 in cancer cells before surgery did not correlate with survival." (PMID 24593279, 2014). "Ultimately, our analysis demonstrated that PSMD1 and PSMD3 mRNA and protein were markedly upregulated in numerous different cancers, which correlated with a worse OS, indicating they may serve as novel prognostic biomarkers in cancer diagnosis and therapy response." (PMID 34572038, 2021).
tumor (28 papers, 2004 to 2026). "Higher PSMD1 expression levels were associated with larger tumor size (p = 0.005), advanced TNM stage (p = 0.015), and increased Edmondson grade (p = 0.005)." (PMID 41535254, 2026). "In the analysis, clinical variables, including AFP level (< 100 vs. ≥ 100 ng/mL) (p = 0.001) and tumor size (< 7 vs. ≥ 7 cm) (p = 0.044) exhibited associations with PSMD1 expression." (PMID 38580756, 2024). "PSMD1 gene encodes a subunit of the proteasome, 19S-RP, which regulates the degradation of various tumor suppressor and oncogenic proteins through the ubiquitin–proteasome pathway." (PMID 38104103, 2023). "Moreover, high expression of PSMD1 indicated a more aggressive tumor phenotype and was associated with poor DFS and OS." (PMID 31413756, 2019). "To explore the potential impact of PSMD1 expression in tumor cells on the tumor microenvironment, we conducted a cell communication analysis." (PMID 41535254, 2026). "PSMD1 knockdown significantly inhibited tumor growth and decreased tumor weight in the xenograft mouse models." (PMID 41535254, 2026). "To investigate the tumor-promoting function of PSMD1 in HCC in vivo, we generated subcutaneous tumor xenograft models in BALB/c nude mice via PSMD1-knockdown MHCC-97H and HCC-LM3 cells." (PMID 41535254, 2026). "Collectively, these findings highlight the inhibitory effect of PSMD1 knockdown on tumor growth in vivo." (PMID 41535254, 2026). "Collectively, these findings suggest that RTKN overexpression modulates the tumor-inhibitory effects of PSMD1 knockdown in HCC." (PMID 41535254, 2026). "We defined tumor cells exhibiting the top 10% of PSMD1 expression as PSMD1-high malignant cells, while the remaining tumor cells were classified as PSMD1-low malignant cells." (PMID 41535254, 2026). "We observed significantly higher PSMD1 mRNA expression in HCC tissues than in adjacent non-tumor liver tissues (NT) (p < 0.001) or normal liver tissues (N) (p = 0.039)." (PMID 38580756, 2024). "Early-stage tumor was more frequent in in low PSMD1 group (45/52, 86.5%) than in high PSMD1 group (6/12, 50%; P = .005)." (PMID 38104103, 2023). "Here we show that the depletion of PSMD1, a component of the proteasomal 19S regulatory complex, is a practical approach to reducing tumor size in the mice xenograft model." (PMID 36934426, 2023). "Previously, we have reported that PSMD1 depletion reduces the 26S/20S ratio accompanied by massive death of a number of aggressive tumor cell lines." (PMID 36934426, 2023). "The aim of this study was to evaluate the prognostic value of PSMD1 expression in tumor tissues of GC patients." (PMID 31413756, 2019). "We also developed two predictive nomograms to assess the risk score for overall survival (OS) and disease-free survival (DFS) of GC patients by integrating parameters such as PSMD1 expression, tumor depth, lymph node metastasis and distant metastasis." (PMID 31413756, 2019). "Tumor growth was significantly inhibited by both PSMD1 knockdown and anti-PD-1 immunotherapy." (PMID 41535254, 2026). "Notably, PSMD1 is highly expressed in HCC tumor tissues and is associated with larger tumor size, more advanced TNM stage, and higher Edmondson grade." (PMID 41535254, 2026). "Subsequent analysis utilizing the CellPhoneDB-secreted ligand‒receptor database revealed that tumor cells with high PSMD1 expression predominantly employ ligands such as MIF, MDK, and SPP1 as signaling molecules to communicate with immune cells within the microenvironment." (PMID 41535254, 2026). "Tissue microarray results showed that PSMD1 was highly expressed in tumor tissues." (PMID 41535254, 2026). "We found that PSMD1 depletion robustly inhibited the growth of these tumor cell lines." (PMID 36934426, 2023).